MTOR (mechanistic target of rapamycin kinase)
Diseases named in the same sentence as MTOR in open-access papers (continued):
Sharing a sentence is not in itself a finding about the gene and the disease.
osteoporosis (67 papers, 2015 to 2026). A condition of reduced bone mass, with decreased cortical thickness and a decrease in the number and size of the trabeculae of cancellous bone (but normal chemical composition), resulting in increased fracture incidence. "Dysregulation of mTOR pathways renders bone marrow mesenchymal stem cells (BMSCs) unable to proliferate and differentiate properly, leading to bone loss and osteoporosis." (PMID 37298150, 2023). "In fact, mTOR is a key regulator of osteoclast function, mTOR activation in osteoclast prevents bone loss in a mouse model of osteoporosis." (PMID 35585885, 2022). "An example of hyperfunction causing atrophy is progression of osteoporosis due to osteoclast hyperactivity, which is promoted by mTOR." (PMID 34990845, 2022). "While the mammalian target of rapamycin (mTOR) pathway plays an important role in bone metabolism, the clinical effects of mTOR inhibitors on osteoporosis or fracture risk remain poorly understood." (PMID 35757436, 2022). "Kaempferol has also been found to prevent osteoporosis-induced bone loss in vivo and in vitro, which results from its regulatory effect on the mTOR pathway." (PMID 32620113, 2020). "Only considering the over-representation evidence, we identified another two significant pathways with FDR≤0.20, Insulin signaling pathway and mTOR (mammalian target of rapamycin) signaling pathway, which has been reported to be associated with osteoporosis." (PMID 26390436, 2015). "However, the underlying mechanism by which the PI3K/Akt/mTOR signalling pathway-mediated ferroptosis alleviates osteoporosis remains to be further investigated and revealed." (PMID 40421249, 2025). "The change in the expression of miR‐125b‐5p and the SIRT3/AMPK/mTOR axis, which was accompanied by the induction of autophagy, could be considered the underlying mechanism of the therapeutic properties of luteolin in confronting osteoporosis." (PMID 40104207, 2025). "Literature studies on the regulation of osteoporosis by autophagy mediated by the PI3K/Akt/mTOR signalling pathway." (PMID 40421249, 2025). "The pathophysiology of osteoporosis is multifaceted, and the mechanism targets of mTOR and NF-κB pathways have become key factors for the regulation of bone homeostasis in countless cellular processes." (PMID 40436926, 2025). "The present findings revealed that osteoporosis is associated with the overexpression of miR‐125b‐5p and alteration in the SIRT3/AMPK/mTOR axis, which is followed by the suppression of autophagy in BMSCs and bone tissue." (PMID 40104207, 2025). "Literature studies on the PI3K/Akt/mTOR signalling pathway mediating inflammatory response to regulate osteoporosis." (PMID 40421249, 2025). "By reviewing the included studies, we elucidated the mechanisms by which six pathological mechanisms mediated by the PI3K/Akt/mTOR signalling pathway regulate osteoporosis." (PMID 40421249, 2025). "Literature studies on the regulation of osteoporosis by ferroptosis mediated by the PI3K/Akt/mTOR signalling pathway." (PMID 40421249, 2025). "According to immunosuppressive therapies, the prevalence of osteoporosis in KTRs treated with tacrolimus, cyclosporine, and mTOR inhibitors (including sirolimus and everolimus) was 14% (95% CI 9–19), 17% (95% CI 9–25), and 22% (95% CI 10–34), respectively." (PMID 40540041, 2025). "Literature studies on the regulation of osteoporosis by the PI3K/Akt/mTOR signalling pathway mediated apoptosis." (PMID 40421249, 2025). "The PI3K/Akt/mTOR signalling pathway is an important intracellular signal transduction pathway that plays a crucial role in the occurrence and development of osteoporosis." (PMID 40421249, 2025). "Concurrently, si‐PMAIP1 can up‐regulate the expression of p‐AMPK and down‐regulate the expression of p‐mTOR to promote the proliferation and differentiation of osteoblasts and inhibit osteoporosis." (PMID 40681473, 2025).
osteoporosis (continued). "In recent years, research on the relationship between the PI3K/Akt/mTOR signalling pathway and osteoporosis has increased." (PMID 40421249, 2025). "Literature studies on the regulation of osteoporosis by oxidative stress mediated by the PI3K/Akt/mTOR signalling pathway." (PMID 40421249, 2025). "In conclusion, oxidative stress can affect the function of bone cells and the balance of bone metabolism, and the PI3K/Akt/mTOR signalling pathway mediates oxidative stress and plays a bidirectional regulatory role in the development of osteoporosis." (PMID 40421249, 2025). "E2 and vitamin D played a synergistic effect on preventing osteoporosis in vivo by inhibiting the mTOR/NFκB signaling pathway." (PMID 40436926, 2025). "Recent studies have focused on exosomes, bone regeneration, and mTOR signaling pathways in macrophage research within the context of osteoporosis." (PMID 38982570, 2024). "The present study showed that salivary nitrate promotes the proliferation and osteogenic differentiation of BMSCs through the EGFR and mTOR signaling pathways, thereby preventing osteoporosis." (PMID 38562945, 2024). "Accumulating evidence indicated that mTOR signaling was activated in osteoporosis, and inhibition of mTOR signaling attenuated the osteoporotic phenotype in mice." (PMID 38126583, 2024). "In conclusion, the journey to unravel the therapeutic potential of the mTOR-autophagy axis in osteoporosis is only beginning." (PMID 39595628, 2024). "Our findings suggest that nitrate enhances the osteogenic differentiation potential of BMSCs by regulating EGFR and mTOR signaling pathways, thereby preventing the osteoporosis." (PMID 38562945, 2024). "The main active component of P. lobata, puerarin, prevented osteoporosis in ovariectomized (OVX) animal models by regulating the autophagy inhibitor mammalian target of rapamycin (mTOR)." (PMID 37435569, 2023). "The PI3K/AKT/mTOR pathway is regulated by Naringin and is involved in the development of glucocorticoid-induced osteoporosis." (PMID 36568515, 2022). "More research shows that inhibiting the PI3K/AKT/mTOR pathway has the same benefit in LPS-induced kidney injury, neurodegeneration, and osteoporosis." (PMID 35681421, 2022). "After treating osteoblasts with AKT/mTOR pathway inhibitors, it is further proved that QGY exerts anti-osteoporosis effects through AKT/mTOR pathway." (PMID 35073518, 2022). "QGY inhibits the combination of CKIP-1 and AKT in osteoblasts, activates the AKT/mTOR signaling pathway, inhibits autophagy, and promotes cell differentiation, thereby exerting an anti-osteoporosis effect." (PMID 35073518, 2022). "We proved that PI3K/Akt/mTOR inhibitors can protect skin against atrophy and extended this observation using osteoporosis model." (PMID 35198100, 2022). "In vivo and in vitro, experiments previously showed that SIRT1 promotes resveratrol-treated osteoblasts autophagy to protect against osteoporosis via activating the PI3K-Akt-mTOR signaling pathway." (PMID 34711685, 2021). "Combined with the results of KEGG and PPI network, PI3K/Akt and mTOR signaling pathways were predicted to be the possible targets for ZG to exert its anti-osteoporosis effect." (PMID 34658868, 2021). "The PI3K/Akt/mTOR signalling pathway regulates the functional balance between osteoblasts and osteoclasts by mediating apoptosis, autophagy, oxidative stress, the inflammatory response, and ferroptosis, thereby alleviating osteoporosis." (PMID 40421249, 2025). "Additionally, an ovariectomized (OVX) osteoporosis mouse model was established to ‌systematically examine‌ the effects of E2, vitamin D, and their combination on osteoporosis and mTOR/NFκB signaling pathway." (PMID 40436926, 2025). "In vivo experiments further revealed that E2 and vitamin D could synergistically prevent osteoporosis in OVX mice by inhibiting the mTOR/NFκB signaling pathway." (PMID 40436926, 2025).
osteoporosis (continued). "Abnormal activation or inhibition of the PI3K/Akt/mTOR signalling pathway can disrupt the balance between osteoblast-mediated bone formation and osteoclast-mediated bone resorption, ultimately leading to the development of osteoporosis." (PMID 40421249, 2025). "In conclusion, we found that salivary nitrate could enhance the proliferation and osteogenic differentiation potential of BMSCs through the EGFR/AKT/ERK and mTOR/S6K signaling pathways, promote bone formation and prevent osteoporosis." (PMID 38562945, 2024). "RhoA promoted osteoclast development via the Akt-mTOR-NFATc1 signaling pathway, resulting a osteoporosis phenotype, and that manipulating RhoA activity might be a therapeutic strategy for osteoporotic bone loss." (PMID 37020186, 2023). "For example, the activation of the PI3K/AKT/mTOR signaling pathway by cholesterol could inhibit autophagy during osteoclast differentiation, thereby worsening osteoporosis." (PMID 37298150, 2023). "Another animal study showed that endogenous Aβ might induce osteoporosis via mTOR-dependent inhibition of autophagy in bone marrow mesenchymal stem cells (BMSCs)." (PMID 37635980, 2023). "MTOR also has a protective effect on ferroptosis in BMSCs, and autophagy mediated by the MTOR pathway can regulate the regeneration function of BMSCs, thereby influencing the occurrence and development of osteoporosis in postmenopausal women." (PMID 36093072, 2022). "Thus, OG prevented senile osteoporosis through attenuating oxidative stress and autophagy of osteoclast via activating Nrf2/Keap1 and mTOR signaling pathway." (PMID 35585885, 2022). "Long-term research on rapamycin, a well-known mTOR inhibition drug, for the treatment of osteoporosis in both experiments and clinical studies has added confidence in the clinical application of leonurine for the treatment of osteoporosis in the future." (PMID 35681421, 2022). "Furthermore, the latest research indicates that suppression of the PI3K/AKT/mTOR pathway is a protective factor in glucocorticoid-induced osteoporosis." (PMID 33708763, 2021). "Furthermore, 36 hub genes of XLGB, such as EGF, EGFR, MTOR, MAPK14 and NFKB1, were considered potential therapeutic targets, suggesting the underlying mechanisms of XLGB acting on osteoporosis." (PMID 32620113, 2020). "Based on experimental data collected in vivo and vitro studies, this study reveals that resveratrol treatment protected osteoblasts in osteoporosis rats by activating the PI3K/Akt/mTOR signaling pathway through enhancing mitophagy via up-regulating the expression of SIRT1." (PMID 31804494, 2019). "Moreover, Western bolt analysis showed that expression of SIRT1, LC3, and Beclin-1 in osteoblasts increased, while p-AKT and p-mTOR were downregulated in osteoporosis rats with high dose resveratrol treatment." (PMID 31804494, 2019). "Identification of such modulators or effectors will also allow for development of agonists of the mTOR-dependent pathways that may be useful for stimulating bone growth in the case of osteoporosis and bone fractures." (PMID 29423330, 2018). "Furthermore, in vivo experiments demonstrated that E2 and vitamin D could synergistically prevent osteoporosis in OVX mice by inhibiting the mTOR/NFκB signaling pathway." (PMID 40436926, 2025). "Therefore, the PI3K/Akt/mTOR signalling pathway may become an effective therapeutic target for osteoporosis in the future." (PMID 40421249, 2025). "Therefore, in-depth research on the mechanism of the PI3K/Akt/mTOR signalling pathway in bone metabolism and its relationship with other signalling pathways will provide new methods for the prevention and treatment of osteoporosis." (PMID 40421249, 2025). "Therefore, this review focuses on summarising the research data from animal cell experiments and clarifies the role of the PI3K/Akt/mTOR signalling pathway in osteoporosis, aiming to provide new ideas and potential therapeutic targets for the treatment of osteoporosis." (PMID 40421249, 2025).
osteoporosis (continued). "However, the pathogenesis of osteoporosis involves multiple signalling pathways, and a recent network pharmacological and molecular analysis preliminarily verified that angelicin could exert anti-osteoporosis effects through the PI3K/AKT/mTOR pathway." (PMID 38956695, 2024). "Therefore, QGY targeting CKIP-1 to regulate the AKT/mTOR-autophagy signaling pathway may represent a promising drug candidate for the treatment of osteoporosis." (PMID 35073518, 2022). "In addition, MON’s anti-osteoporosis effects by an autophagy activation via the AKT/mTOR signaling pathway and maybe help to alleviate muscle atrophy in myotubes and muscle tissues through this pathway." (PMID 35565825, 2022). "Furthermore, quercetin may exert biological effects on osteoporosis with metabolic disorders and may be associated with the GPRC6A/AMPK/mTOR signaling pathway." (PMID 35547008, 2022). "Our findings demonstrated that E2 and vitamin D exhibited synergistic efficacy in preventing osteoporosis by modulating the miR-351-5p/IRS1 axis and inhibiting the mTOR/NFκB signaling pathway." (PMID 40436926, 2025). "In conclusion, E2 and vitamin D exhibited a synergistic effect in preventing osteoporosis through the miR-351-5p/IRS1 axis and mTOR/NFκB signaling pathway." (PMID 40436926, 2025). "The mechanisms of anti‐osteoporosis were predominant in the Wnt, PIK3‐AKT, Notch, mTOR, and MAPK signaling pathways." (PMID 40192033, 2025). "This study confirms that E2 and vitamin D synergistically ameliorate osteoporosis by inhibiting the miR-351-5p/IRS1 axis and the mTOR/NFκB pathway." (PMID 40436926, 2025). "In terms of bone and joint protection, the mechanisms of the protective effects on osteoporosis or osteoarticular disease involve regulation of the signaling of caspase-3/9, Bax/Bcl-2, PI3K/Akt/mTOR, Glo1-AGE-RAGE, AKT/Erk, and NF-κB signaling." (PMID 39301568, 2024). "Many signaling pathways involved in osteoporosis have been explored, including OPG/RANKL/RANK, Wnt/β-catenin, PI3K/Akt/mTOR, MAPK, and Hedgehog." (PMID 37476411, 2023). "We used the model of Gc-induced osteoporosis in mice and demonstrated the potency of PI3K/Akt/mTOR modulators to diminish bone resorption induced by Dex." (PMID 35198100, 2022). "Our findings indicate that quercetin can reduce the osteoporosis induced by testosterone deficiency, and its beneficial effects might be associated with the regulation of glucose metabolism and inhibition of lipid metabolism via the GPCR6A/AMPK/mTOR signaling pathway." (PMID 35547008, 2022). "In order to study the molecular mechanism of QGY improving osteoporosis, the expression of related proteins in the autophagy pathway mediated by CKIP-1 and AKT/mTOR was evaluated." (PMID 35073518, 2022). "It is speculated that QGY may inhibit autophagy, activate the AKT/mTOR pathway, reduce the expression of CKIP-1 and RANKL, and promote the expression of RUNX2 and OPG, thereby improving osteoporosis." (PMID 35073518, 2022). "In this study, resveratrol treatment increased SIRT1-induced mitophagy in the DEX-treated osteoblasts via PI3K/Akt/mTOR signaling pathway, which suggested that the PI3K/Akt/mTOR signaling pathway might be a target for osteoporosis therapy." (PMID 31804494, 2019). "Importantly, QGY treatment promotes osteoblast differentiation and enhances osteogenic capacity by targeting CKIP-1 mediated AKT/mTOR pathway activation and autophagy inhibition (rather than osteoclasts), thereby playing a role in improving osteoporosis." (PMID 35073518, 2022). "Thus, paeoniflorin may alleviate DEX-induced osteoporosis by promoting osteogenic differentiation and autophagy via inhibition of the AKT/mTOR signaling pathway." (PMID 33880124, 2021).
metastatic disease (66 papers, 2008 to 2026). "In fact, high p-mTOR QS is associated with poorer prognosis in our study, as it correlated with the presence of metastatic disease at diagnosis and a shorter disease-free survival after radical resection." (PMID 29213282, 2017). "We also conclude that this patient may benefit from an mTOR inhibitor in case of disease recurrence since his metastatic disease carries an activating mTOR mutation and cancer cells cultured from his lung tumor showed vulnerability to mTOR inhibition." (PMID 30176882, 2018). "The metastatic tumor also had an activating MTOR mutation, which may be important for tumor metastasis." (PMID 30176882, 2018). "In conclusion, the coexpression of caveolin-1 and activated components of the AKT/mTOR pathway represents a ‘linked molecular signature’ that identifies patients with localised RCC that are at high risk of developing metastatic disease that warrants greater postoperative surveillance." (PMID 18283322, 2008). "This supports future investigation of targeted mTOR‐based therapy, particularly for inoperable or metastatic diseases." (PMID 41479435, 2026). "Then, the expression profiles of SNAIL and mTOR were examined in the primary and their matched metastatic tumors of the patients and both mRNAs were determined to be higher in liver tissues." (PMID 40566531, 2025). "In the metastatic tumor, mTOR, KRAS and MYC were found to be up regulated compared with normal liver tissues (p < 0.05)." (PMID 40566531, 2025). "Cut off values of SNAIL and mTOR expressions in the metastatic tumor were determined and the patients were divided into two groups: high expression and low expression." (PMID 40566531, 2025). "In summary, our results warrant the exploration of CDK8/19i for the treatment of TNBC, both as single agents, with activity against the metastatic disease, and as combinations with approved drugs, in particular mTOR and AKT inhibitors." (PMID 39541354, 2024). "In tumor metastases, the mammalian target of rapamycin (mTOR) signaling pathway plays an important role and mTOR inhibitors have been clinically employed for the treatment of some metastatic tumors." (PMID 38163890, 2024). "The SMAD4 gene is frequently mutated in PCa, correlates with changes in altered histopathological transitions, metastatic disease, and poor prognosis and is associated with a higher mortality rate in patients receiving anti-EGFR/Akt/mTOR therapy." (PMID 38329726, 2024). "PTEN is also a known negative regulator of the PI3K/AKT/mTOR pathway, and studies have reported a significant association between the loss of PTEN expression and metastatic disease." (PMID 38023131, 2023). "One patient was then treated with Everolimus (mTOR inhibitors) with clinical response (metastatic tumor shrinkage)." (PMID 37938323, 2023). "In a study using pre-clinical ILC models, inhibition of mTOR signaling (using an mTORi) blocked the growth of ILC primary tumors as well as the progression of metastatic disease." (PMID 36539444, 2022). "Even though our results suggested low mTOR activity in most of the samples, we found significantly higher H-scores of rictor in primary metastatic diseases." (PMID 35392503, 2022). "Limited-stage disease treatment mainly consists of surgery, while for advanced and metastatic disease, somatostatin analogs, mTOR inhibitors, PRRT, and cytotoxic chemotherapy control symptoms and provide a limited survival benefit." (PMID 35163032, 2022). "Therapies that target the phosphatidylinositol 3-kinase (PI4K)-mammalian target of rapamycin (mTOR) such as everolimus (an mTOR inhibitor) and PIK3Cα inhibitors have also shown to be effective in combination with endocrine therapy in metastatic disease." (PMID 33671468, 2021). "The first-line treatment in patients with metastatic disease includes systemic therapy by using multitarget tyrosine kinase inhibitors (TKIs) and mammalian target of rapamycin (mTOR) inhibitors." (PMID 31772326, 2020).